CRP (C-reactive protein)
Diseases named in the same sentence as CRP in open-access papers (continued):
Sharing a sentence is not in itself a finding about the gene and the disease.
non-alcoholic fatty liver disease (57 papers, 2008 to 2026). "Subjects with Acute-on-Chronic Liver Failure (ACLF) and Non-Alcoholic Fatty Liver Disease (NAFLD) have also elevated serum CRP concentrations, which has also been reported as an independent risk factor for NAFLD." (PMID 37873776, 2023). "High anti-CRP IgG levels were found also in all hepatitis C patients, whereas only a few autoimmune hepatitis and Non-alcoholic Fatty Liver Disease (NAFLD) sera were positive." (PMID 37873776, 2023). "CRP is often elevated in nonalcoholic fatty liver disease, suggesting that the accumulation of hepatic adipose tissue is associated with enhanced inflammation-mediated oxidative stress." (PMID 36418968, 2022). "C-reactive protein (CRP) of serum is another strong index predicting incidence of nonalcoholic fatty liver disease." (PMID 35154608, 2021). "There is evidence that serum CRP levels has a significant positive relationship with non-alcoholic fatty liver disease severity." (PMID 33203036, 2020). "In the multivariate analyses, LBP was associated with high sensitive C-reactive protein (hs-CRP) and non-alcoholic fatty liver disease (NAFLD) fibrosis score (NFS) before weight management in the obese group." (PMID 30458048, 2018). "Recently, it has been reported that the severity of non-alcoholic fatty liver disease correlates with high-sensitivity CRP values." (PMID 21190397, 2011). "The non-traditional cardiovascular risk factors that we studied were the following: hs-CRP, TG/HDL ratio, ApoA1, ApoB, ApoB/ApoA1 ratio, leptin, adiponectin, homocysteine, IL-2, IL-4, IL-6, IL-10, IL-17A, TNF-α and INF-γ, and non-alcoholic fatty liver disease (NAFLD)." (PMID 37892418, 2023). "We performed a follow-up study to address whether high sensitivity C-reactive protein (hs-CRP) levels within the normal range can predict the development of non-alcoholic fatty liver disease (NAFLD) in healthy male subjects." (PMID 28234943, 2017). "Chronic consumption of Chlorella vulgaris (300 mg/day) for eight weeks by people with non-alcoholic fatty liver disease (NAFLD), improved glycemic status as well as C-reactive protein and measures of liver function." (PMID 35206005, 2022). "In that study, the reduction in CRP and TNF-α as well as other liver enzymes was measured after the treatment of non-alcoholic fatty liver disease." (PMID 29564059, 2018). "This outcome is consistent with MR studies in other disease contexts, where observational studies have shown significant associations between CRP and diseases like cancer, CVD, and non-alcoholic fatty liver disease, but the MR analysis failed to establish direct relationships." (PMID 39859220, 2025). "It demonstrated a negative correlation between RHGS and CRP, and nonalcoholic fatty liver disease." (PMID 38802799, 2024). "Indeed, there is growing evidence that diet and nutrients can influence the pathophysiology of non-alcoholic fatty liver disease (NAFLD); where the fatty liver overproduces the liver enzymes ALT, AST, and gamma-glutamyltransferase (GGT), C-reactive protein (CRP), and coagulation factors." (PMID 37582773, 2023). "Previous studies have indicated that variants of the high sensitive C-reactive protein (CRP), Interleukin (IL)-6 and leptin receptor (LEPR) genes are associated with the presence of obstructive sleep apnea (OSA) but not in non-alcoholic fatty liver disease (NAFLD) in Asian Indians." (PMID 30001365, 2018).
Parkinson disease (55 papers, 2011 to 2025). A progressive degenerative disorder of the central nervous system characterized by loss of dopamine producing neurons in the substantia nigra and the presence of Lewy bodies in the substantia nigra and locus coeruleus. "The colocalization evidence for Parkinson’s disease (coloc.abf-PPH4 = 0.725) moderately supports its association with CRP." (PMID 39229261, 2024). "The neuroinflammatory process in Parkinson's disease is associated with elevated Hs-CRP levels therefore, raised levels of CRP are found to be associated with a higher risk of development of Parkinson's disease." (PMID 36381804, 2022). "Although publications indicate that CRP is associated with the pathogenesis of neurological disorders and deemed to be a "risk factor" for Parkinson's disease (PD), the evidence exists still indefinitely." (PMID 31057478, 2019). "This study investigated the association between CRP concentrations and functional motor deterioration in patients with PD using the Unified Parkinson’s Disease Rating Scale Part III (UPDRS-III) score." (PMID 26308525, 2015). "The elevation of plasma homocysteine (Hcy) and C-reactive protein (CRP) has been correlated to an increased risk of Parkinson's disease (PD) or vascular diseases." (PMID 21556377, 2011). "Alternatively, worse parkinsonism may predispose a person to the alteration of Hcy and CRP due to some medication factors, such as L-dopa treatment." (PMID 21556377, 2011). "A study of patients with Parkinson’s disease determined hs-CRP levels in patients with freezing of gait (FOG)." (PMID 38338653, 2024). "Positive results from the colocalization analysis have revealed shared genetic signals within the genetic locus linking CRP with Parkinson’s disease and asthmatic pneumonia." (PMID 39229261, 2024). "People with Parkinson’s disease have been reported to have increased levels of C-reactive protein (CRP) and inflammatory cytokines." (PMID 36432051, 2022). "There are a few references to the use of salival Abeta42 in diagnosing AD, of saliva alpha-synuclein as a biomarker for Parkinson’s disease and progressive supranuclear palsy, and quite a few on saliva levels of CRP in heart disease and atherosclerosis I." (PMID 32019214, 2020). "On the other hand, a recent high-stress situation, urine incontinence, Parkinson’s disease, increase in the BMI, CRP, Charlson comorbidity index (CCI), and Timed Up and Go (TUG) test scores significantly diminished the SEH." (PMID 27387416, 2016). "Multivariate models of effect of baseline C-reactive protein (CRP) on change in Unified Parkinson’s Disease Rating Scale Part III (UPDRS-III) score for the entire follow-up period, as estimated by a generalized estimation equation model." (PMID 26308525, 2015). "Interestingly, correlations between CRP levels in CSF and the Movement Disorder Society-sponsored revision of the unified Parkinson’s disease rating scale (MDS-UPDRS) III and Montreal Cognitive Assessment (MoCA) scores have been detected." (PMID 38392998, 2024). "Moreover, baseline CRP has also been reported as a predictor of mortality in patients with Parkinson’s disease." (PMID 29954339, 2018). "Neuroinflammation plays a key role in the pathogenesis of Parkinson disease, and inflammatory markers like C-reactive protein (CRP) and monocyte chemotactic protein-1 (MCP-1) in cerebrospinal fluid (CSF) were demonstrated to be associated with nonmotor features of PD." (PMID 27688826, 2016). "Elevated plasma CRP concentrations before the onset of parkinsonism may therefore have an enduring effect on motor prognosis." (PMID 26308525, 2015). "For Parkinson’s disease, the colocalization evidence (coloc.abf-PPH4 = 0.725) moderately supports a link with CRP." (PMID 39229261, 2024). "A single RCT for PD found a significant improvement in the Unified Parkinson’s Disease Rating Scale (UPDRS), as well as a reduction in CRP and an improvement in insulin sensitivity." (PMID 37298527, 2023).
Parkinson disease (continued). "Conversely, age, comorbidities (Parkinson’s disease), the number of drugs prescribed at admission, FIM–T, FIM-M, FIM-C, and CRP were significantly different between the two groups." (PMID 35631262, 2022). "The observation concerning CRP, SAA and IL-8 was also confirmed in an analysis evaluating correlations with the III part of the Unified Parkinson’s Disease Rating Scale (UPDRS)." (PMID 33809527, 2021). "Further, very similar correlations were obtained between Parkinson’s Disease Rating Scale-3 (UPDRS-3) and CSF inflammatory markers where the UPDRS-3 score correlated with CRP (p = 0.025, β = 0.138), SAA (p < 0.001, β = 0.205), IL-8 (p = 0.032, β = 0.134) and MCP-1 (p = 0.020, β = 0.150)." (PMID 30185816, 2018). "Plasma concentrations of high-sensitivity CRP were measured in the absence of infections, and the Unified Parkinson’s Disease Rating Scale Part III (UPDRS-III) scores were measured at five follow-up intervals (Days 1–90, 91–270, 271–450, 451–630, and 631–900)." (PMID 26308525, 2015). "Several studies have confirmed that abnormal IL-6, CRP, TNF-α, IL-4, IL-8, and TGF-β levels were associated with worse motor function assessed by the Unified Parkinson’s Disease Rating Scale (UPDRS), whereas CRP and fractalkine might be potential markers of freezing of gait (FOG)." (PMID 36739284, 2023).
peripheral vascular disease (55 papers, 2008 to 2025). Any disorder affecting blood flow through the veins or arteries outside of the heart. "Uric acid has also been associated with increased inflammatory markers such as C-reactive protein which have been implicated in peripheral vascular disease." (PMID 25197282, 2014). "Markers of inflammation, such as CRP, are related to the risk of cardiovascular and peripheral vascular disease." (PMID 18439295, 2008). "On the other hand, CRP was prominent and present in most terms in the final model when RA/CA was interrogated by multiple regression suggesting that innate immune processes may be implicated in the observed opioid-vasculopathy effect." (PMID 24889849, 2014). "High‐sensitivity CRP (hs‐CRP) has been reported to be a better predictor of inflammatory response and vascular disorders than CRP." (PMID 38895772, 2024). "The presented data do not implicate VEGF or its downstream effector CEACAM-114 in the process of CRP vasculopathy as the latter generally increases with time." (PMID 39132647, 2023). "Despite these issues and the fact that most CRP research to date has focused on vascular disorders, there is mounting evidence that CRP isoforms have distinct biological properties, with nCRP often exhibiting more anti-inflammatory activities compared to mCRP." (PMID 29706967, 2018). "The serum levels of TNF-α, IL-6, and C-reactive protein (CRP) were also higher in subjects with arteriosclerotic peripheral vascular disease compared to healthy controls." (PMID 24766841, 2014). "In univariate Cox regression, patient's age, the presence of peripheral vascular disease, serum albumin, and C-reactive protein and creatinine clearance were independent predictors of all-cause mortality." (PMID 24959538, 2013). "• In our study, rosuvastatin improved endothelial function (FMD) and decreased CRP levels suggesting a possible link between inflammation and vasculopathy in SSc." (PMID 24008003, 2013). "Findings from this study indicate that mortality in stable dialysis patients, when categorized by ESA dosage and [Hb], is related primarily to age, CRP, dialysis duration and peripheral vascular disease (PVD)." (PMID 22702540, 2012). "Possibly, the best way to view CRP is as a continuum that may take one of three forms, inflammation-predominant, vasculopathy-predominant, or mixed." (PMID 39132647, 2023). "Additionally, CRP levels are known to increase with age, and mCRP has been shown to play a role in the pathogenesis of peripheral vascular diseases including cardiovascular diseases and poststroke inflammation." (PMID 34687487, 2021). "High-sensitivity CRP (hsCRP) is a better predictor of vascular disorders than CRP." (PMID 31396293, 2019). "Because CRP levels increase with age and mCRP plays a role in the pathogenesis of peripheral vascular diseases including cardiovascular diseases and poststroke inflammation, we hypothesized that mCRP plays some roles causing cerebrovascular pathology for the vascular risk of AD." (PMID 34687487, 2021). "Recent study showed that HDL function was impaired in heart transplant recipients but it was not related to cardiac allograph vasculopathy and CRP levels." (PMID 26648662, 2015).
pulmonary embolism (55 papers, 2015 to 2025). The obstruction of the pulmonary artery or one of its branches by an embolus, sometimes associated with infarction of the lung. "There are a lot of factors that can be associated with higher rates of pulmonary embolism during hospitalization, for example D-dimer and CRP levels." (PMID 35625480, 2022). "Factors such as CRP levels can be linked to higher rates of pulmonary embolism during hospitalization." (PMID 35625480, 2022). "In addition to Wells score, PECSS identified seven clinical predictors (anhelation, abnormal blood pressure, in critical condition when admitted, age > 65 years and high levels of pro-BNP, CRP and UA,) strongly associated with pulmonary embolism." (PMID 37550677, 2023). "Data on demographics, comorbidities, device use, laboratory values at diagnosis (D-dimer, platelet count, C-reactive protein (CRP), liver/renal function), treatment, and outcomes (mortality, pulmonary embolism, bleeding) were collected." (PMID 40507388, 2025). "A complete blood count was within normal limits, with a CRP level of 16.8 mg/l and D-dimer concentration of 900 μg/l, which raised suspicion of pulmonary embolism." (PMID 39010032, 2024). "In the pulmonary embolism group, levels of CRP, WBC, neutrophils, lymphocytes, hemoglobin, SII, NLR, and MII-1 were significantly lower after thrombolytic treatment compared to their levels before the treatment (p<0.05)." (PMID 39742171, 2024). "A complete blood count was within normal limits, but a slightly elevated CRP level of 16.8 mg/l and D-dimer concentration of 900 μg/l raised suspicion of pulmonary embolism." (PMID 39010032, 2024). "Neutrophil levels were positively correlated with the pulmonary embolism severity index score (r = 0.357, P < 0.001), high sensitive C-reactive protein, D-dimer and pulmonary artery obstruction index (PAOI), in the overall population of APE patients." (PMID 36918857, 2023). "Similar to another study, compared to baseline, inflammatory markers (C-reactive protein and fibrinogen) had lower values at pulmonary embolism diagnosis." (PMID 35566758, 2022). "In contrast, the increase in C-reactive protein observed in patients undergoing to pulmonary embolism suggests the crucial role of inflammation in the pathogenesis of thrombotic complications in patients affected by SARS-CoV 2 infection." (PMID 33585520, 2020). "Compared to other data in the literature, where inflammation markers, such as CRP and ferritin, could be predictors of pulmonary embolism, we identified D-dimers as the only discriminator of patients with this condition." (PMID 40428888, 2025). "Based on univariate analyses, six parameters were identified as significant predictors of pulmonary embolism (PE) and were selected for the construction of the Hema-PE Score: D-dimer/albumin ratio, immobility, central venous catheter, C-reactive protein (CRP), platelet count, and hemoglobin." (PMID 41156207, 2025). "Few GPs also used a high count of neutrophil granulocytes as a sign of bacterial infection or as a supplement to their interpretation of the CRP test, while several GPs described using oxygen saturation to assess the severity of dyspnoea or to diagnose pulmonary embolism." (PMID 34205866, 2021). "The unfavorable group had higher baseline inflammatory markers (leukocytes, CRP, ferritin, and D-dimer), had received treatment with dexamethasone less often, but treatment with methylprednisolone in high dose more often, and had a higher incidence of pulmonary embolism." (PMID 37622126, 2023). "We identified cutoff values of D-dimer required to rule out pulmonary embolism for CKD-EPI eGFR as well as for CRP by achieving a negative predictive value of 0.99 and 0.95, respectively." (PMID 38353879, 2024). "OCT was able to detect small distal pulmonary artery thrombosis in patients with a negative CT scan for pulmonary embolism and elevated thromboinflammatory markers (i.e., high D-dimer, CRP, IL-6, or ferritin)." (PMID 36873865, 2023).
pulmonary embolism (continued). "C-reactive protein (CRP) is an acute-phase protein synthesized mainly by hepatocytes in response to various stimuli like bacterial infections, inflammation, malignancy, and pulmonary embolism." (PMID 35874904, 2022). "In one study, a significant difference in C-reactive protein and D-dimer between PE positive and PE negative patients was observed, which may suggest that COVID-19 positive patients with higher levels of inflammation and D-dimer values are more susceptible to developing pulmonary embolism." (PMID 33969266, 2021). "For example, anastomotic leakage could induce a stronger inflammatory response than non-infective complications as pulmonary embolism and may explain this CRP cut-off rate difference between the literature and our study." (PMID 36387256, 2022). "Patients with widespread parenchymal abnormalities, with or without pulmonary embolism, had increased main pulmonary artery diameter (p < 0.05) and higher C-reactive protein (p < 0.01), D-dimer (p < 0.01), and troponin T (p < 0.001) and lower hemoglobin (p < 0.001)." (PMID 34268322, 2021). "However, increases of CRP are also seen in non-infective pathologies such as pulmonary embolism, trauma and malignancies." (PMID 26937636, 2016). "Lastly, patients who have high levels of inflammatory markers, such as CRP and LDH, and high-density consolidation (especially more than one pulmonary lobe) on imaging may also have higher MP loads and subsequent persistent MP airway infection that is accompanied by NP, AO, or pulmonary embolism." (PMID 31823740, 2019). "The differences between the two groups in terms of pulmonary embolism, bronchial necrosis, the erythrocyte sedimentation rate (ESR), and the C-reactive protein level were not statistically significant." (PMID 41163588, 2025).